CYP1B1 (cytochrome P450 family 1 subfamily B member 1)
Diseases named in the same sentence as CYP1B1 in open-access papers (continued):
Sharing a sentence is not in itself a finding about the gene and the disease.
renal cell carcinoma (15 papers, 2004 to 2025). "To assess the expression of CYP1B1 ex vivo, we performed immunohistochemistry assays on biopsies of healthy human kidney tissue and cisplatin-treated renal cell carcinoma (RCC)." (PMID 37371125, 2023). "Differential CYP1B1 expression was also observed in different clinical stages and tumor grades, and a high expression of CYP1B1 was also observed in renal cell carcinoma, which was related to advanced grades and late stages." (PMID 36428734, 2022). "The expression profile of CYP1B1 is suggestive to have a potential role as a biomarker and target for anti-cancer therapy for renal cell carcinomas and ovarian cancers." (PMID 33692504, 2021). "Nevertheless, the CYP1B1 finding, that acts as a well-known oncogenic protein in renal cell carcinoma by the Aryl Hydrocarbon Receptor Signaling suggested an unexplored link between aberrant Complement activation, DNA damage and tumorigenesis." (PMID 31284268, 2019). "We reported that CYP1B1 expression is regulated by miR-200c and high CYP1B1 levels contribute to resistance of renal cell carcinoma (RCC) to docetaxel." (PMID 28388569, 2017). "Cytochrome P450 1B1 (CYP1B1) has been shown to be up-regulated in many types of cancer including renal cell carcinoma (RCC)." (PMID 26626260, 2015). "A recent study performed by the group of Murray identified CYP1B1 activity in renal cell carcinoma using an activity assay based on the O-deethylation of 7-ethoxyresorufin and the use of the CYP1A1/CYP1B1 inhibitor α-napthoflavone." (PMID 24358191, 2013). "Despite high protein expression and enzymatic activity of cytochrome P450 1B1 (CYP1B1) in renal cell cancer (RCC), its functional significance has not been elucidated." (PMID 25860934, 2015). "Notably, McFadyen and colleagues showed a higher CYP1B1 expression in renal cell carcinoma when compared to the normal kidney." (PMID 31382511, 2019).
endometrial cancer (13 papers, 2010 to 2025). Primary or metastatic malignant neoplasm involving the endometrium (mucous membrane that lines the endometrial cavity). "Finally, the CYP1B1*2 355T allele was also reported to be associated with an increased susceptibility to other cancers, such as breast and endometrial cancer." (PMID 25299224, 2014). "Immunohistochemical staining of endometrial carcinomas showed that CYP1B1 is upregulated in endometrial cancers." (PMID 38566107, 2024). "The impact of CYP1B1 on the progression of the cell cycle in endometrial cancer cells and its role in regulating the expression of various genes associated with the cell cycle have been observed." (PMID 38566107, 2024). "For instance, the transcription of CYP1B1 was induced in breast and endometrial cancer cells by E2 through the activation of ERα and its binding to an estrogen responsive element (ERE) located within the CYP1B1 promoter sequence." (PMID 29290975, 2017). "The downregulation of CYP1B1 has also been reported in melanoma and endometrial cancer, although many other reports have contradictory observations and demonstrated the upregulation of CYP1B1 in endometrial tumors." (PMID 22114726, 2011). "In particular, evaluating PA’s ability to suppress CYP1B1-mediated estrogen metabolism or chemoresistance in breast, ovarian, or endometrial cancer cell lines could offer valuable translational insight." (PMID 40883330, 2025). "Thus unlike the previous reports in mouse Leydig cells and endometrial cancer, the downregulation of CYP1B1 does not seem to be governed by estrogen." (PMID 22114726, 2011).
cardiac hypertrophy (12 papers, 2018 to 2026). "Studies have shown that CYP1B1 enzyme and its associated cardiotoxic intermediate metabolite hydroxyeicosatetraenoic acids (HETEs) exert direct effects on the development of myocardial hypertrophy." (PMID 41526548, 2026). "Studies in rats have demonstrated that elevated CYP1B1 activity is linked to pathological conditions such as cardiac hypertrophy, vasoconstriction, endothelial dysfunction, and increased ROS production." (PMID 41487507, 2025). "CYP1B1-mediated production of mid-chain HETEs have been implicated in the pathogenesis of cardiac hypertrophy, and in doxorubicin (DOX)-induced cardiotoxicity." (PMID 33185690, 2020). "Confirming the causative role of CYP1B1 in developing cardiac hypertrophy, overexpression of CYP1B1 using CRISPR technology has been shown to induce cellular hypertrophy in the cardiac-derived RL-14 cells." (PMID 33185690, 2020). "The 6β-OHT treatment brought back the effect of Ang II to cause aortic hypertrophy in Cyp1b1−/− and castrated Cyp1b1+/+ and Cyp1b1−/− mice as indicated by increased media to lumen ratio of the aorta (respectively)." (PMID 31948482, 2020). "Despite the need for further investigation, CYP1B1 may have noteworthy therapeutic implications for cardiac hypertrophy and AS/PH that are the important underlying mechanisms of CVD31." (PMID 37848499, 2023). "To reiterate, our results may shed light on the role of CYP1B1 and its associated mid-chain HETEs metabolite in the development of cardiac hypertrophy and suggest that CYP1B1 could be used a novel target in the treatment of pressure overload-induced cardiac hypertrophy." (PMID 29426916, 2018). "Cytochrome P450 1B1 (CYP1B1) and its related cardiotoxic HETEs metabolites have been identified as directly contributing to the development of cardiac hypertrophy." (PMID 39599599, 2024). "The relation between the level of CYP1B1 enzyme and the induction of cardiac hypertrophy due to the increase in the production of midchain HETEs has been well-established." (PMID 39188949, 2024). "The upregulation of CYP1B1 and its cardiotoxic metabolites, midchain HETEs, is a prevalent feature in various diseases and conditions, including inflammation, cancer, and cardiac hypertrophy." (PMID 39188949, 2024). "Intriguingly, the anti-fungal drug fluconazole has been shown to inhibit CYP1B1 and protect against angiotensin II-induced cardiac hypertrophy." (PMID 33185690, 2020). "Castration attenuated the increase in vascular reactivity, endothelial dysfunction, vascular hypertrophy, and fibrosis in Ang II-infused Cyp1b1+/+ mice." (PMID 31948482, 2020). "Inhibition of CYP1B1 has also been recently shown to prevent uremic toxins-induced cardiac hypertrophy." (PMID 33185690, 2020). "El-Kadi and colleagues demonstrated that cardiac CYP1B1 expression was up-regulated in different models of cardiac hypertrophy induced by isoproterenol, pressure overload, angiotensin II, and polycyclic aromatic hydrocarbons." (PMID 33185690, 2020). "In the present study, the effect of 6β-OHT to restore the Ang II-induced increase in BP and aortic hypertrophy that was reduced by castration in Cyp1b1+/+ mice was inhibited by flutamide." (PMID 31948482, 2020). "This is of some importance to the role of the AhR and CYP1B1 in cardiac hypertrophy, as both kynurenine and kynurenic acid activate the AhR to increase CYP1B1." (PMID 31434333, 2019). "Other CYP1B1 metabolites have been shown to contribute to cardiac hypertrophy, including 6β-hydroxytestosterone." (PMID 31434333, 2019). "Additionally, 2-methoxyestradiol, a specific CYP1B1 inhibitor, protected against pressure overload-induced cardiac hypertrophy via antioxidant and anti-inflammatory properties." (PMID 33185690, 2020). "Importantly, inhibition of CYP1B1-mediated mid-chain HETEs production has been shown to prevent cardiac hypertrophy in male rats." (PMID 33185690, 2020). "Increased CYP1B1 is evident in cardiac hypertrophy, including when induced by dasatinib." (PMID 31434333, 2019).
cardiac hypertrophy (continued). "Both CYP1B1 and CYP1A1 were reported to be upregulated in the hearts of rats treated with isoprenaline-induced cardiac hypertrophy." (PMID 39188949, 2024). "CYP1B1 can metabolize AA into cardiotoxic metabolites exemplified as mid-chain hydroxyeicosatetraenoic acid (HETE), and 20-HETE is involved in the pathogenesis of cardiac hypertrophy and the consequent cardiac remodeling." (PMID 37784143, 2023).
colon carcinoma (12 papers, 2008 to 2025). "Meta-analysis of clinical studies indicated that a CYP1B1 polymorphism was associated with a wide variety of cancers, including lung cancer, breast cancer, and colon cancer." (PMID 38612589, 2024). "Meta-analyses of clinical investigations have indicated that polymorphic variants of CYP1B1 associate with diverse malignancies including lung, breast, and colon cancers." (PMID 38612589, 2024). "However, another study found a lower frequency of mutation allele CYP1B1 4326G in patients with colon cancer, indicating that this allele may reduce the risk of colon cancer and even exert a protective effect." (PMID 25299224, 2014). "Previous studies have demonstrated that CYP1B1 is overexpressed in colon cancers, and that the enzymatic activity is significantly higher in tumor specimens compared to normal colon tissue." (PMID 27111221, 2016). "Over-expression of CYP1A1 and CYP1B1 in human colon tumors implies a pro-carcinogenic role for AhR target genes." (PMID 26264025, 2015). "Rutin targets two proteins, namely NT5E and EGFR, which both interact with established colon cancer drug targets and two proteins that are part of the colon cancer prognostic signature gene set (CYP1B1 and ALOX5)." (PMID 24886433, 2014). "The finding that CYP1B1 active protein is differentially expressed in bladder and colon tumors strongly supports its use for anticancer therapy." (PMID 24358191, 2013). "CYP1B1 mRNA levels were significantly lower in 6 out of 20 colon tumors compared to normal epithelia, whereas patients 13 and 4 presented non significant difference in CYP1B1 mRNA levels between normal and tumor tissues." (PMID 24358191, 2013). "CYP1B1 mRNA was overexpressed in 65% and 60% of bladder and colon tumors respectively, whereas CYP1A1 was overexpressed in 65% and 80% of bladder and colon tumors." (PMID 24358191, 2013). "Importantly, CYP1B1 expression was validated using colon cancer tissue as a positive control, and the inhibition of such expression was confirmed using a blocked CYP1B1 antibody." (PMID 41155673, 2025). "Notably, these results also differ from our previous study, where 5-FU increased the mRNA expression of CYP1A1 and CYP1B1 in the same colon cancer cell lines." (PMID 40649986, 2025). "Although many other CYP isoforms contribute to these processes and their analysis could provide additional valuable insights, we focused on CYP1A1 and CYP1B1 because these isoforms are frequently overexpressed in colon cancer cells." (PMID 40649986, 2025). "As a next step, our studies will explore the underlying mechanisms of how WD modulates B(a)P biotransformation enzymes (CYP1A1, CYP1B1, glucuronosyltransferase, sulfotransferase, and glutathione-S-transferases) and increases the number of colon tumors compared to RD." (PMID 26959117, 2016). "Cytochrome P450 1B1 (CYP1B1) is a monooxygenase that is highly expressed in many tumors, such as brain, breast and colon tumors, which has led to a strong interest in the role of CYP1B1 in tumorigenesis." (PMID 36085146, 2022). "This is one of the few studies that substantiate the implication of CYP1B1 and CYP1A1 to a lesser extent, in cancer therapy due to their differential enzyme activity overexpression in bladder, and colon tumors." (PMID 24358191, 2013). "Mean mRNA levels of CYP1B1 and CYP1A1 along with mean CYP1 activity were higher in bladder and colon tumors compared to normal tissues (p<0.05)." (PMID 24358191, 2013). "These in silico findings, together with great effects on SW-480 and HT-29 colon cancer cells, provide a foundation for further experimental validation and characterization of isorhamnetin’s interactions with target proteins, including CYP1A1, CYP1B1, P-gp, MRP1, and MRP5." (PMID 40649986, 2025).
colon carcinoma (continued). "When mean expression levels of CYP1A1 and CYP1B1 mRNA were compared in the entire panel of bladder or colon tissues the analysis indicated that expression levels of CYP1A1 and CYP1B1 mRNA were higher in bladder and colon tumors compared to normal tissues (p < 0.05)." (PMID 24358191, 2013). "Gibson and coworkers reported in 2003 that CYP1B1 protein expression does not possess a direct role in tumor invasion as the level of CYP1B1 expression in stage 1 (pT1 and pT2) was not significantly different than that of stage 2 colon tumors (pT3 and pT4) in a sample size of 61 colon tumors." (PMID 24358191, 2013).
cervical carcinoma (10 papers, 2015 to 2024). A carcinoma arising from either the exocervical squamous epithelium or the endocervical glandular epithelium. "piR-14633 was observed to promote proliferation, migration, and invasion of cervical cancer cells by METTL14/CYP1B1 signaling axis." (PMID 38182573, 2024). "The aim of this study was to examine CYP1B1 expression in cervical cancers and to assess the enzyme’s relationship with several clinicopathological features." (PMID 34636736, 2021). "In light of all these reports, differences in the CYP1B1 expression between normal and tumor cervical tissues supports the development of potential therapeutic approaches for cervical cancer." (PMID 34636736, 2021). "CYP1B1 expression in normal cervical tissues and all subtypes of cervical cancer tissues was significantly different (P=.01)." (PMID 34636736, 2021). "Immunohistochemistry was performed to examine CYP1B1 expression in 100 patient samples with cervical cancer and 10 patient samples with normal healthy cervical tissues." (PMID 34636736, 2021). "In this study, for the first time, we describe high CYP1B1 expression in cervical cancers, in particular, in squamous cell carcinoma." (PMID 34636736, 2021). "Given that no previous studies have examined the expression of CYP1B1 in cervical cancers, this study aims to assess the aberrant expression of CYP1B1 in cervical cancer and its relation to baseline demographic and clinicopathologic features." (PMID 34636736, 2021). "In conclusion, this study is the first to characterize CYP1B1 overexpression in cervical cancers compared to low CYP1B1 expression in the corresponding normal cervical tissues adjacent to tumors." (PMID 34636736, 2021). "METTL14, also an oncogene in cervical cancer, enhanced its m6A methylation levels by being mediated by piRNA-14633 (PIWI-interacting RNA-14633) to activate the piRNA-14633/METTL14/CYP1B1 axis which promoting the proliferation, invasion and metastasis of cervical cancer cells." (PMID 38343637, 2024). "Other cervical cancer subtypes included in this study also displayed CYP1B1 overexpression." (PMID 34636736, 2021). "The differential profile of CYP1B1 expression between cervical cancer tissues and normal cervical tissues suggests that CYP1B1 may be used as a target for future therapeutic exploitations." (PMID 34636736, 2021). "In this study, we showed that the expression of CYP1A1, AIP, CYP1B1, ESR1, and MAF was significantly correlated with the level of T cell infiltration in cervical cancer." (PMID 34784845, 2021). "Studies have reported that CYP1B1 was expressed in the majority of the cervical cancer samples (91/100, 91.0%) but not in normal healthy cervical samples." (PMID 35093098, 2022). "CYP1B1 was expressed in the majority of the cervical cancer samples (91/100, 91.0%) but not in normal healthy cervical samples." (PMID 34636736, 2021). "The main finding of this study is that CYP1B1 was selectively expressed in cervical cancers and not in normal cervical tissues, thereby making it a potential target for future development of CYP1B1-based therapeutic strategies." (PMID 34636736, 2021). "However, neither of these studies have investigated CYP1B1 expression in cervical cancer." (PMID 34636736, 2021).
renal carcinoma (10 papers, 2014 to 2025). A carcinoma arising from the epithelium of the renal parenchyma or the renal pelvis. "Several case–control studies were performed to identify the association of CYP1B1 polymorphisms with prostate, bladder and renal cancer risk." (PMID 24913727, 2014). "Previous studies have reported the existence of CYP1B1 L432V missense polymorphism in prostate, bladder and renal cancers." (PMID 24913727, 2014). "The authors used several renal cancer cell lines to show this association and proved that miR-200c directly targets CYP1B1 and the low expression of miR-200c in these cell lines is correlated with an increased expression of CYP1B1." (PMID 35582590, 2019). "The polymorphisms of the CYP1B1 gene at codons 119 and 432 might be risk factors for renal cancer, especially in the male population." (PMID 26537097, 2015). "Enhanced ADAM12 and CYP1B1 expression promotes tumorigenesis of renal cancer since their silencing reduces the tumor growth and cancer cell proliferation and migration." (PMID 39806854, 2025). "The novel aspect of our work is that we not only found two genes (ADAM12 and CYP1B1) upregulated in CAAs of renal cancer but also, we observed that their expression correlates with BMI and is tightly linked with the overweight‐to‐obese degree of patients." (PMID 39806854, 2025). "As expected, CYP1B1 is highly expressed in renal carcinoma, whereas healthy kidney tissue displays a low expression of this protein." (PMID 37371125, 2023). "The expression of CYP1B1 by tARPC was confirmed by analyzing biopsies of cisplatin-treated renal carcinoma patients that showed the colocalization of CYP1B1 with the tARPC marker CD133." (PMID 37371125, 2023). "The CD133/CYP1B1 renoprotective role has been also showed by our overall survival analysis on 200 renal cancer patients, highlighting a better outcome for patients expressing high levels of ARPC." (PMID 37371125, 2023). "Using several renal cancer cell lines, miRNA-200c has been shown to directly target CYP1B1, which is overexpressed upon downregulation of this miRNA." (PMID 35205839, 2022). "Looking at TCGA database, significance was found for CYP1B1 expression relevant to bladder and kidney carcinoma." (PMID 32626511, 2020). "TCGA database analysis showed increased survival at bladder and renal carcinoma when CYP1B1 expression is low." (PMID 32626511, 2020). "We found that the expression of CYP1B1 was quite heterogeneous among the several types of tumors and that it is often lower in normal tissues compared to tumoral tissues, as in the case of renal cancers." (PMID 37371125, 2023). "MiRNA-200c is involved in the regulation of CYP1B1 in renal cancer cells and docetaxel resistance." (PMID 35205839, 2022). "Therefore, we analyzed miR-200c expression in microdissected human renal cancer tissues and matched adjacent normal regions, which were used for the CYP1B1 expression study (n = 24)." (PMID 25860934, 2015). "Moreover, we performed an overall survival analysis of patients with two different renal cancers (renal clear cell and renal papillary cell carcinoma) based on the renal Prominin 1 (CD133) gene expression normalized on the total CYP1B1 gene expression." (PMID 37371125, 2023).